MIR4255 (microRNA 4255)
Synonyms: hsa-mir-4255
Gene: MicroRNA gene on chromosome 1 (37,161,563 to 37,161,634, forward strand). Ensembl gene ENSG00000264698.
Homologues: Orthologues: chimpanzee MIR4255 (100% identical).